ST6GAL1 (ST6 beta-galactoside alpha-2,6-sialyltransferase 1)
Diseases named in the same sentence as ST6GAL1 in open-access papers (continued):
Sharing a sentence is not in itself a finding about the gene and the disease.
cancer (107 papers, 2009 to 2025). A tumor composed of atypical neoplastic, often pleomorphic cells that invade other tissues. "ST6GAL1 has become increasingly dominant in sialyltransferase activity, which are implicated in cancer." (PMID 39290304, 2024). "Previous studies have linked the specific sialyltransferase, ST6GAL1, in the hypersialylation of β1 integrins which then leads to increased cell adhesion and migration in various cancers." (PMID 38673867, 2024). "The level of 2,6 sialylation is an important marker of cancer progression as α2,6-galactoside sialyltransferase 1 (ST6Gal1) upregulation has been linked to aggressiveness of cancer cells including colorectal, gastric carcinoma, lungs, and brain." (PMID 39628991, 2024). "ST6GAL1 emerges as a potential cancer-associated glycosyltransferase in thyroid malignancies, offering valuable insights into its diagnostic and prognostic significance." (PMID 38003522, 2023). "One of the predominant glycan changes in a cancer cell is an increase in α2,6-linked sialic acids on N-glycans, which occurs, in part, as a consequence of ST6GAL1 upregulation." (PMID 37660914, 2023). "RNA-Seq analyses of GEM pancreata indicate that ST6GAL1 activity upregulates stem- and cancer-associated gene networks, promotes a pancreatic ductal cell program, and induces activation of EGFR." (PMID 37643018, 2023). "Altered glycosylation is a hallmark of cancer, and increased ST6GAL-1 mRNA and protein have been found in multiple types of cancer, including ovarian, pancreatic, and colonic cancers." (PMID 35041825, 2022). "In recent years, a large number of studies have suggested that upregulation of ST6GAL1 has been associated with tumor aggressiveness in various cancers." (PMID 36547200, 2022). "ST6GAL1 is a key player in cancer development since it catalyzes the addition of α2,6-linked sialic acids to terminal N-glycans." (PMID 36297573, 2022). "Aberrant glycosylation is a universal feature of cancer cells, and ST6GAL1 is reported to be associated with aggressive, invasive disease with chemoresistance in numerous cancers." (PMID 34980201, 2022). "The sialyltransferase ST6GAL1 that adds α2–6 linked sialic acids to N-glycans of cell surface and secreted glycoproteins is prominently associated with many human cancers." (PMID 35676533, 2022). "Overall, analysis using TCGA and METABRIC cohorts revealed that elevated ST6GAL1 is associated with enrichment in gene networks associated with cancer stemness (Hedgehog), epithelial-mesenchymal transition (EMT), and hypoxia pathways." (PMID 35676533, 2022). "Recently, the activity of ST6GAL1 was found to be increased in cancer tissues and the increased ST6GAL1 activity was shown to be associated with several hallmark properties of cancer." (PMID 35159178, 2022). "Altered glycosylation is a cancer hallmark, and ST6GAL1 is one of the main glycosyltransferases upregulated in malignancies." (PMID 36345944, 2022). "Cancer cell-native ST6GAL1 is preferentially released in association with exosome-like particles and smaller exomere-like particles." (PMID 35676533, 2022). "Increased expression of β-galactoside α2,6-sialyltransferase I (ST6GAL1), an enzyme generated α2,6-sialylated lactosamine, is often associated with invasive phenotype and poor prognosis in several cancers, including colon, stomach, and ovarian cancers." (PMID 34745942, 2021). "ST6GAL1 is upregulated in numerous cancer types and has recently been linked to all of the cancer hallmarks." (PMID 31614918, 2019). "For example, ST6GAL1 is a proto-oncogene linked to poor prognosis across an array of cancers (including breast) where expression is correlated with promoter methylation." (PMID 29847599, 2018). "As for the high expression of α2,6‐sialylated glycans observed across both cancer types, we have previously shown that ST6GAL1, responsible for the synthesis of α2‐6‐linked N‐glycans, was upregulated in all of the four cancer cell lines previously tested." (PMID 28853212, 2017).
cancer (continued). "This unmethylated configuration of the ST6GAL1 promoter correlated with a strong ST6GAL1 expression in both cell lines UROtsa and RT4, whereas a weak expression in J82 and a nearly complete loss of ST6GAL1 mRNA expression in RT112 cancer cells was observed." (PMID 25465919, 2014). "ST6GAL1 and its associated glycans are likely to be an important target in cancer cells." (PMID 39272811, 2024). "Many studies have associated high levels of ST6GAL1 expression with clinicopathological parameters such as advanced tumor grade, lymphovascular invasion, metastatic progression, and overall survival in different types of cancer." (PMID 38003522, 2023). "The activation of cancer-associated networks in SC cells aligns with the concept that ST6GAL1 upregulation induces molecular signaling events and transcriptomic changes that may predispose cells to neoplastic transformation." (PMID 37643018, 2023). "The ability of extracellular ST6GAL1 to compensate for the deficiency in cell-native ST6GAL1 expression may provide a new perspective in understanding the role of this sialyltransferase in cancer." (PMID 35676533, 2022). "Interestingly, SOX2 and ST6GAL1 are located within the same tumor-associated amplicon, 3q26, and these two genes exhibit coordinate gains in copy number across multiple cancers including ~ 25% of ovarian serious adenocarcinomas." (PMID 31610800, 2019). "In addition, altered expression of ST6Gal1 is associated with adhesion and metastasis of cancer cells." (PMID 30542051, 2018). "In cancers, elevated ST6Gal-1 expression is often associated with poor prognosis." (PMID 30294329, 2018). "Consistent with its role in fostering ADM, ST6GAL1 promotes progenitor-like characteristics in other stemness-associated processes, including epithelial to mesenchymal transition, acquisition of cancer stem cell properties, and the reprogramming of somatic cells into induced pluripotent stem cells." (PMID 39260693, 2024). "Indeed, more than one fourth of high-grade cancer tissues showed complete loss of ST6GAL1 protein." (PMID 25465919, 2014). "As shown in cancer tissue, both ST6GAL1‐high and ‐low epithelial cells were mainly located in niche 0–7 and niche 13–14, forming the cancer nest." (PMID 40847469, 2025). "Next to being a cancer cell survival factor, ST6GAL1 also protects tumors from hypoxia through the modulation of cancer cell metabolism." (PMID 40885395, 2025). "ST6GAL1 influences cancer progression not only through direct sialylation of substrates but also by modulating other processes beyond PTMs." (PMID 39937175, 2025). "Our study shows that the ST6GAL1 soluble form is transferred from human donor cancer cells to (human or murine) recipient cancer cells via sEVs." (PMID 40938891, 2025). "ST6GAL1-mediated α2–6 sialylation of TNFR1 promotes cancer cell survival by preventing TNFR1 oligomerization, high-affinity TNF binding, and subsequent internalization." (PMID 40885395, 2025). "Given the suggested role of ST6GAL1 in cancer progression, we assessed its expression in the human PrCa cell lines PC3, DU145 and C4-2B, which portray a range of disease progression and their derived sEVs." (PMID 40938891, 2025). "ST6GAL1 is upregulated upon chemotherapy, preventing cancer cell apoptosis and thus reducing treatment efficacy." (PMID 40885395, 2025). "The expression of ST6GAL1 is enriched in both stem/progenitor cells and cancer cells when compared with many differentiated epithelial cell types." (PMID 39615678, 2024). "The increase in α2,6 sialylation of N-glycans is driven by the sialyltransferases ST6GAL1, which is overexpressed in numerous cancer types and are fundamental for tumor growth, metastasis, immune evasion, and drug resistance." (PMID 39628991, 2024). "Previous studies have shown ST6GAL1-mediated α2-6 sialylation impacts cancer hallmarks and regulates oncogenic cell behaviours, however the specific targets and signalling pathways orchestrated by ST6GAL1 require greater delineation." (PMID 38772281, 2024).
cancer (continued). "In tandem with transcriptional activation, ST6GAL1 is upregulated in cancer cells through gene amplification." (PMID 39260693, 2024). "The increased α2,6 sialylation on N-glycans catalyzed by β-galactoside α2,6 sialyltransferase 1 (ST6Gal1) is frequently observed in many cancers." (PMID 38958800, 2024). "ST6GAL1 is overexpressed in several cancer types and plays a fundamental role in tumour transformation, growth, metastasis, and immune evasion." (PMID 38772281, 2024). "Taken together, these results show that at concentrations lower than the IC50 for cytotoxicity, FCW393 inhibits ST6GAL1 activity selectively, integrin sialylation, and cancer cell migration." (PMID 38673867, 2024). "The β-galactoside α2,6 sialyltransferase 1 (ST6Gal1), an enzyme catalyzing the α2,6 sialylation on N-glycans, has been well investigated because the altered expression of ST6Gal1 is observed in many kinds of cancer cells and tissues." (PMID 38958800, 2024). "ST6GAL1 is an important sialyltransferase enzyme which is upregulated in many tumour types and plays a key role in cancer progression." (PMID 38772281, 2024). "Sialylation mediated by sialyltransferase enzymes is one of the main glycosylation processes altered in cancer and one principal sialyltransferase overexpressed in a plethora of malignant diseases is ST6GAL1." (PMID 38003522, 2023). "This is further supported by the pancreas-specific genetic deletion of ST6GAL1 in a mouse model, which delays cancer formation." (PMID 37372117, 2023). "Although there are 20 different human sialyltransferases, ST6GAL1 is amongst the most studied sialyltransferases in cancer research." (PMID 38003522, 2023). "Recent studies indicated that ST6Gal1 is a crucial enzyme in the sialylation of N-glycans and plays essential roles in the immune system, pathogen recognition, and cancer biology." (PMID 36622466, 2023). "Extensive literature has documented ST6GAL1 overexpression in a plethora of human cancers; however, knowledge regarding ST6GAL1’s functional contribution to carcinogenesis remains limited." (PMID 37643018, 2023). "Although ST6Gal-1 is known as the main player in sialic-acid-related cancer progression and therapeutic resistance, sialyltransferase ST3Gal1 has also been linked to cancer progression and drug resistance." (PMID 37894470, 2023). "Levels of ST6GAL1 were upregulated in numerous types of cancers, including prostate, pancreatic, ovarian, colon, cervical, gastric, breast cancer, and glioma." (PMID 38003522, 2023). "Here, our data suggest that certain cancer cells have the capacity to significantly raise the local extracellular ST6GAL1 levels." (PMID 35676533, 2022). "To date, ST3GAL1 and ST6GAL1 have been the most commonly investigated and targeted sialyltransferase enzymes in cancer." (PMID 36077781, 2022). "While ST6Gal1 has received some attention recently, important questions still remain unresolved to distinguish ST6Gal1 as a cancer biomarker." (PMID 36106023, 2022). "We found, contrary to expectations, the majorityof miRNAs upregulate ST6GAL1 and α-2,6-sialylation in a varietyof cancer cells." (PMID 36439307, 2022). "First, the data suggest the importance of cancer cell ST6GAL1 in several important cancer cell phenotypes, including cell proliferation and invadopodia formation." (PMID 35676533, 2022). "Extracellular ST6GAL1, present in cancer exosomes or the freely soluble recombinant sialyltransferase, compensates for insufficient intrinsic ST6GAL1 by boosting cancer cell proliferation and increasing invasiveness." (PMID 35676533, 2022). "There is also substantial evidence that ST6GAL1 plays an important role in cancer progression, and is overexpressed in numerous cancers including colorectal." (PMID 35467766, 2022). "Exosome-like particles from ST6GAL1-high cancer cells elicit increased cell proliferation and invasiveness in cancer cells with less native ST6GAL1 expression." (PMID 35676533, 2022).
cancer (continued). "Elevated cancer ST6GAL1 is often correlated with high tumor grade, metastasis, and poorer patient prognosis." (PMID 35676533, 2022). "Upregulation of ST6Gal1 is observed in many malignancies, and a large body of research has determined that ST6Gal1-mediated α2,6 sialylation impacts cancer hallmarks." (PMID 36106023, 2022). "Located within the 3q26 amplicon, they are amplified in cancer cells, and due to the binding of the transcribed Sox2 to ST6GAL1, its expression is enhanced further." (PMID 36547200, 2022). "This α2,6 sialylation by ST6Gal1 is not only a prognostic marker for select cancers but also a driver of malignant progression." (PMID 36106023, 2022). "For ST6GAL1, which is known to be upregulated in many cancers, upregulation appears to be the major mode ofaction of miRNA, although these same miRNAs have downregulatory activityfor other genes." (PMID 36439307, 2022). "Here, we demonstrate that extracellular ST6GAL1 elicits definitive phenotypic consequences in the recipient cells in the forms of enhanced cancer cell proliferation, growth, and invasive behavior." (PMID 35676533, 2022). "Our work also suggests that upregulatorymiRNAs enhance overexpression of ST6GAL1 and α-2,6-sialylation,providing another potential pathway to explain the dysregulation observedin cancer and other disease states." (PMID 36439307, 2022). "It is within the cell-autonomous context that ST6GAL1 involvement in cancer progression has been interpreted." (PMID 35676533, 2022). "Canonically, ST6GAL1 is localised intracellularly within the trans-Golgi network, and it is within this context that the role of ST6GAL1 in cancer biology has been interpreted." (PMID 36077781, 2022). "The sialyltransferase ST6GAL1 modifies glycans and glycoproteins important not only in cancer progression but also in the maintenance of cancer stem cell phenotype." (PMID 35676533, 2022). "Recently, an OMICS network analysis investigating adhesion proteins revealed that sialylation of adhesion molecules, specifically by ST6Gal1, plays a vital role in cancer cell EMT, migration and invasion." (PMID 36106023, 2022). "Our data further suggest the presence of undefined cofactors within the cancer exosomes, and these cofactors potentiate the action of extracellular ST6GAL1." (PMID 35676533, 2022). "Fifth and most unexpectedly, although cancer exosomes devoid of ST6GAL1 cargo are unable to promote tumor cell survival, cell proliferation, and invadopodia formation, these properties are restored upon the addition of soluble recombinant ST6GAL1." (PMID 35676533, 2022). "While there is much to be investigated about phenotypic effects of ST6Gal1 in cancers, even more information is needed on the ST6Gal1-mediated signals that lead to protumorigenic cellular behaviors." (PMID 36106023, 2022). "It has been shown that ST6GAL1 expression also correlates with poor tumour prognosis and affects multiple mechanisms related to cancer, suggesting that the immune effect is not limited to infection." (PMID 35784319, 2022). "It is apparent that ST6Gal1 plays a central role in cancer pathobiology, and thus holds a great potential for anti-cancer therapeutics." (PMID 36106023, 2022). "ST6GAL1 packaged within cancer exosomes can cell-surface sialylated and elicit signaling in recipient target cells." (PMID 35676533, 2022). "There have been other studies that have investigated alterations in apoptosis as the mechanism of resistance mediated by ST6GAL-1 in other types of cancer." (PMID 35041825, 2022). "Beyond colon and liver cancers, ST6Gal1-mediated activation of the PI3K/AKT axis has also been reported in fibroblasts as well as other cancer types." (PMID 36106023, 2022). "The expression of β-galactoside α2,6-sialyltransferase (ST6Gal1) is altered in several cancers, including colon, stomach, and ovarian." (PMID 35744954, 2022). "ST6GAL1 is also implicated in the epithelial to mesenchymal transition (EMT) and can promote a cancer-stem-cell phenotype." (PMID 36077781, 2022).